XRCC3 (X-ray repair cross complementing 3)
Diseases named in the same sentence as XRCC3 in open-access papers (continued):
Sharing a sentence is not in itself a finding about the gene and the disease.
pancreatic cancer (6 papers, 2011 to 2025). "The primary aim of the current investigation is to elucidate the potential role of the XRCC3 Thr241Met polymorphism as a risk factor in the development of pancreatic cancer." (PMID 38918791, 2024). "The XRCC3 Thr241Met polymorphism has been identified as contributing to a reduced risk of pancreatic cancer in the Caucasian population." (PMID 38918791, 2024). "In numerous genetic studies, a strong correlation was found between the XRCC3 Thr241Met polymorphism and the risk of pancreatic cancer." (PMID 38918791, 2024). "Prior research exploring the correlation between the XRCC3 Thr241Met polymorphism and the susceptibility to pancreatic cancer has yielded conflicting outcomes." (PMID 38918791, 2024). "In summary, our findings suggest that the XRCC3 Thr241Met polymorphism is associated with a reduced risk of pancreatic cancer in Caucasian populations." (PMID 38918791, 2024). "The analysis revealed significant associations between the XRCC3 Thr241Met polymorphism and an increased risk of pancreatic cancer." (PMID 38918791, 2024). "So far, plenty of studies have evaluated the XRCC3 C18067T polymorphism with cancers risk, including colorectal, bladder, lung, breast, pancreatic cancer and so on." (PMID 24454720, 2014). "Therefore, this study aims to apply evidence-based medicine principles and methods to conduct a comprehensive analysis of all published studies on the relationship between XRCC3 Thr241Met polymorphism and genetic susceptibility to pancreatic cancer." (PMID 38918791, 2024). "The XRCC3 Thr241Met gene polymorphism has been linked to pancreatic cancer development." (PMID 38918791, 2024). "Pancreatic cancer showed an exceptionally high biallelic loss in HRR genes, with BRCA1, CDK12, FANCC, PPP2R2 A, RAD51 C, RAD51D, RAD52, WRN, and XRCC3 all presenting 100% biallelic loss." (PMID 40420266, 2025).
head and neck cancer (5 papers, 2012 to 2016). A primary or metastatic malignant neoplasm affecting the head and neck. "Since that report, two more articles evaluating the relationship between XRCC3 polymorphisms and the risk of radiation-induced adverse effects in head and neck cancer (HNC) patients have been published, and they were included in the present meta-analysis." (PMID 26091483, 2015). "A meta-analysis of case-control studies identified that the XRCC3 241M allele may act as a head and neck cancer risk factor among all subjects." (PMID 25013509, 2014).
osteosarcoma (5 papers, 2015 to 2024). A usually aggressive malignant bone-forming mesenchymal neoplasm, predominantly affecting adolescents and young adults. "Our main analysis identified significant associations with osteosarcoma for 12 variants in 8 genes: CTLA-4, ERCC3, IL-8, PRCKG, RECQL5, TNF-α, XRCC3, and VEGF." (PMID 38360742, 2024). "The pooled ORs of 12 variants in 8 genes (CTLA-4, ERCC3, IL-8, PRCKG, RECQL5, TNF-α, XRCC3, and VEGF) were significantly associated with the risk of osteosarcoma in the main analysis." (PMID 38360742, 2024). "In prior meta-analyses, associations of genetic polymorphisms in VEGF, MDM2, CTLA-4, TNF-a, TNF-b1, PRCKG, RECQL5, XRCC3, and GST with osteosarcoma susceptibility were investigated." (PMID 38360742, 2024). "Given that CHO cells deficient for RAD51C, RAD51D, XRCC2 or XRCC3, and human HCT116 cells deficient for XRCC3 are viable, we attempted to disrupt each classical RAD51 paralog individually in transformed human osteosarcoma U2OS and human embryonic kidney HEK293 cells." (PMID 31584931, 2019).
squamous cell carcinoma (5 papers, 2007 to 2020). A carcinoma arising from squamous epithelial cells. "We therefore conclude that hypermethylation of homologous recombination DNA repair genes including RAD51B and XRCC3 is associated with an inflamed phenotype in squamous cell cancers of the head and neck, lung and cervix." (PMID 27683114, 2016). "As a result, we found that XRCC3 C18067T polymorphism was associated with decreased risk of both basal cell carcinoma and squamous cell carcinoma." (PMID 24454720, 2014). "This XRCC3 variant genotype was associated with significantly decreased survival in squamous cell carcinoma." (PMID 23443124, 2012). "Interestingly, RAD51B and XRCC3 promoter methylation has been reported in association with the inflamed phenotype of squamous cell carcinomas of the head and neck, lung, and cervix, warranting further investigation as predictive biomarkers of response to immunotherapy." (PMID 32295201, 2020). "For squamous cell carcinoma, patients with Thr/Met genotype at XRCC3 showed a significantly shorter survival time than those with the Thr/Thr genotype (13 months versus 48 months; log-rank test, p < 0.0001)." (PMID 23443124, 2012). "In this study, XRCC3 Thr241Met might be an independent prognostic factor in squamous cell carcinoma." (PMID 23443124, 2012). "Two homologous recombination genes, X-Ray Repair Complementing Defective Repair in Chinese Hamster Cells 3 (XRCC3) and RAD51 Paralog B (RAD51B) exhibited the highest correlation with CD274 and CTLA4 across all three squamous cell cancer types." (PMID 27683114, 2016).
xeroderma pigmentosum group D (5 papers, 2011 to 2022). Any xeroderma pigmentosum in which the cause of the disease is a mutation in the ERCC2 gene. "For example, variants of genes involved in DNA repair, such as x-ray repair cross complementing 1 (XRCC1), XRCC3, human 8-oxoguanine DNA N-glycosylase 1 (hOGG1), and xeroderma pigmentosum group D (XPD), have been documented in schizophrenia pathophysiology." (PMID 30285728, 2018).
glioblastoma (4 papers, 2019 to 2024). The most malignant astrocytic tumor (WHO grade IV). "Recently, the XRCC3 polymorphism was found to contribute to temozolomide resistance in glioblastoma cells by mediating the repair of DNA double-strand breaks." (PMID 36264998, 2022).
melanoma (4 papers, 2003 to 2022). A malignant, usually aggressive tumor composed of atypical, neoplastic melanocytes. "Furthermore, we observed mutations affecting FGFR4, KLC1 and XRCC3, associated to colon cancer and melanoma." (PMID 35836575, 2022). "In the same way as we have done for XPD and melanoma, study of XRCC3 flanking markers will be required to rule out roles for linkage disequilibrium and population stratification in the association found." (PMID 12865926, 2003).
colon cancer (3 papers, 2017 to 2022).
endometriosis (3 papers, 2020 to 2024). The growth of functional endometrial tissue in anatomic sites outside the uterine body. "Endometriosis is associated with variants in XRCC3, BRCA1 and CSB genes." (PMID 39359934, 2024).
gastric cancer (3 papers, 2016 to 2024). A primary or metastatic malignant neoplasm involving the stomach. "Epidemiological data increasingly suggest a link between repair gene polymorphisms and cancer risk, with XRCC3 implicated in various malignancies, including lymphoma, lung, esophageal, salivary gland, colorectal, cervical, breast, and stomach cancers." (PMID 38918791, 2024).
Gynecomastia (3 papers, 2020 to 2022). Abnormal development of large mammary glands in males resulting in breast enlargement. "The RAD51B and XRCC3 signatures can accurately discriminate MaBC from gynecomastia, with normal breast tissues showing methylation of these gene promoters at lower levels than in MaBC, suggesting the existence of a tumorigenesis pathway." (PMID 35373955, 2022). "Remarkably, the methylation panel in tissue samples combining RAD51B and XRCC3 accurately discriminated MBC from gynecomastia." (PMID 34298749, 2021). "Only RAD51B and XRCC3 disclosed statistically significant differences between tumor and gynecomastia tissues, with higher methylation levels observed in gynecomastia tissue samples." (PMID 32295201, 2020). "Assembled in a panel, RAD51B and XRCC3 promoter methylation discriminated male BC from gynecomastia with 91.5% sensitivity, 89.5% specificity, and 91.2% accuracy." (PMID 32295201, 2020). "Remarkably, the methylation panel combining RAD51B and XRCC3 accurately discriminated male BC from gynecomastia, in tissue samples." (PMID 32295201, 2020). "Surprisingly, however, higher RAD51B and XRCC3 promoter methylation levels were disclosed in gynecomastia comparing to male BC." (PMID 32295201, 2020). "In this study we demonstrated that promoter methylation levels of RAD51B and XRCC3 differ between male BC and gynecomastia tissues, suggesting its usefulness, in a panel, as male BC biomarkers." (PMID 32295201, 2020). "ATM, BRCA1, PALB2, RAD51B, and XRCC3 promoter methylation levels were evaluated in paired tumor, normal tissue, and adjacent lymph nodes, and in gynecomastia tissue samples." (PMID 32295201, 2020). "Thus, although RAD51B and XRCC3 promoter methylation levels might be higher in gynecomastia, histone-related factors might preclude effective gene silencing, contrarily to BC." (PMID 32295201, 2020). "The gene promoters that showed statistically significant differences between tumor and gynecomastia samples (RAD51B and XRCC3) were evaluated as potential biomarkers for male BC." (PMID 32295201, 2020). "ATM, BRCA1, PALB2, RAD51B, and XRCC3 have epigenetic signatures in MaBC that are absent in corresponding normal tissue and gynecomastia samples obtained from patients without cancer or with a family history of BC." (PMID 35373955, 2022). "Among the five gene promoters tested, only two - RAD51B and XRCC3—disclosed statistically significant differences between tumor and gynecomastia tissue samples, whereas ATM, BRCA1, and PALB2 did not." (PMID 32295201, 2020). "RAD51 and XRCC3 exhibited consistent staining patterns both in gynecomastia and female breast normal tissue: Intense positive nuclear and cytoplasmatic staining was found for RAD51 in all samples, whereas negative nuclear staining and a weak cytoplasmatic staining was observed for XRCC3." (PMID 32295201, 2020). "The epigenetic signatures of ATM, BRCA1, PALB2, RAD51B, and XRCC3 have also been explored in MBC (32.4% with germline BRCA2 PV) in matched normal and gynecomastia tissue samples (obtained from patients without cancer or a family history of BC)." (PMID 34298749, 2021).
skin cancer (3 papers, 2013 to 2014). "Unfortunately, so far there has not yet a report which comprehensively and specially evaluates all of the previous literature to get a precious estimate of this association between XRCC3 C18067T polymorphism and skin cancer risk." (PMID 24454720, 2014). "In spite of the shortages above, our meta-analysis had also several advantages as follows: First, a meta-analysis of the association of XRCC3 C18067T polymorphism on skin cancer risk is statistically more powerful than any other single study." (PMID 24454720, 2014). "In the past decade, the majority of molecular epidemiologic studies investigated XRCC3 C18067T polymorphism on skin cancer susceptibility." (PMID 24454720, 2014). "The XRCC3 C18067T polymorphism has been reported to be associated with skin cancer susceptibility, yet the results of these previous results have been inconsistent or controversial." (PMID 24454720, 2014). "To derive a more precise estimation of the relationship between XRCC3 C18067T polymorphism and skin cancer risk, we conducted a meta-analysis of all available case-control studies relating the XRCC3 C18067T polymorphism to the risk of developing skin cancer." (PMID 24454720, 2014). "Up to now, a lot of studies have been conducted to investigate the relationship between XRCC3 C18067T polymorphism and skin cancer risk." (PMID 24454720, 2014). "The present meta-analysis was carried out by critically reviewing 15 individual case-control studies on XRCC3 C18067T polymorphism and skin cancer risk." (PMID 24454720, 2014). "The association between the XRCC3 C18067T polymorphism and skin cancer risk was assessed by odds ratios (ORs) together with their 95% confidence intervals (CIs)." (PMID 24454720, 2014). "In summary, this meta-analysis systematically analyzed the association between XRCC3 C18067T polymorphism and the risk of skin cancer." (PMID 24454720, 2014). "Our study was carried out to investigate the association between XRCC3 C18067T polymorphism and skin cancer risk." (PMID 24454720, 2014). "The meta-analysis showed insignificant association between skin cancer and XRCC3 C18067T polymorphism in the overall population." (PMID 24454720, 2014). "Although comprehensive analysis was conducted to show the association between XRCC3 C18067T polymorphism and risk of skin cancer, there are still some limitations should be pointed out." (PMID 24454720, 2014). "Meta-analysis of the XRCC3 C18067T polymorphism with risk of skin cancer." (PMID 24454720, 2014). "So that XRCC3 has been of great interest as a candidate gene for cancers, including skin cancer." (PMID 24454720, 2014). "After screening the titles and abstracts, 10 studies were excluded because they were not relevant to the role of XRCC3 C18067T polymorphism on skin cancer risk." (PMID 24454720, 2014).
triple-negative breast carcinoma (3 papers, 2015 to 2023). An invasive breast carcinoma which is negative for expression of estrogen receptor (ER), progesterone receptor (PR), and human epidermal growth factor receptor 2 (HER2). "Some correlation was observed between the XRCC2-Arg188His and XRCC3-Thr241Met polymorphisms and triple-negative breast cancer invasiveness." (PMID 24728564, 2015). "In the present study, the association between the Arg188His polymorphism of XRCC2 gene and Thr241Met polymorphism of XRCC3 gene and triple-negative breast cancer in the population of Polish women was investigated." (PMID 24728564, 2015). "The obtained data suggest that the reported study may be the first observation of the polymorphisms in XRCC2 and XRCC3 genes, involved in the DNA repair pathway, to be associated with triple-negative breast carcinoma risk in the population of Polish women." (PMID 24728564, 2015). "In conclusion, XRCC2 Arg188His and XRCC3 Thr241Met polymorphisms may be regarded as predictive factors of triple-negative breast cancer in female population." (PMID 24728564, 2015). "Hence, XRCC3 rs1799794 AA is a potential predictive marker for triple negative breast cancer in Saudi women and further investigations in other populations are warranted for universal application in cancer detection and prediction." (PMID 26881229, 2016). "Five other members belonging to the family of homologous recombination repair genes were upregulated by PAC in triple-negative breast-cancer cells (RAD54L, XRCC3, RAD51D, FEN1, and TOP3A) but only RAD54L is common in both types of cell lines (MCF-7 and MDA-MB-231)." (PMID 37298600, 2023).
astrocytoma (2 papers, 2016 to 2017). "For XRCC3, a double-strand break repair gene, the thr241Met polymorphism of XRCC3 has been associated with susceptibility to developing astrocytomas and GBM." (PMID 29152101, 2017). "In conclusion, we investigated an association between XRCC3, XRCC4 and XRCC5 gene polymorphism and the risk and prognosis of astrocytoma in Chinese Han population." (PMID 27852033, 2016). "So, we want to determine the effect of DNA repair genes (XRCC3, XRCC4 and XRCC5) on the prognosis of astrocytoma in our research." (PMID 27852033, 2016). "In this study, we want to explore the relationship between DNA repair genes (XRCC3, XRCC4 and XRCC5) and prognosis of astrocytoma in the Chinese Han population." (PMID 27852033, 2016).
breast tumors (2 papers, 2011 to 2019). "Indeed, the size distribution of deletions and the presence of a few other types of non-clustered rearrangements in RAD51C−/−, XRCC2−/−, XRCC3−/−, BRCA2−/−, or PALB2−/− mutant cells closely resembled the predominant rearrangement signature of BRCA2-deficient breast tumors." (PMID 31727117, 2019).
diabetic nephropathy (2 papers, 2023 to 2025). "XRCC3, a DNA repair gene, has been significantly associated with T2D and diabetic nephropathy in a Turkish population." (PMID 39827095, 2025). "Recently an association between other members of the same protein family (XRCC1 and XRCC3) and diabetic nephropathy has been suggested." (PMID 36769128, 2023).
liver cancer (2 papers, 2016 to 2020). An epithelial or non-epithelial malignant neoplasm that arises from the liver. "Such complexes may elucidate why XRCC3 polymorphisms are risk factors in AFB1-associated liver cancer." (PMID 32994210, 2020).
lung squamous cell carcinoma (2 papers, 2012 to 2016). "The XRCC3 Thr241Met gene polymorphism may be a prognostic factor in lung squamous cell carcinoma patients." (PMID 23443124, 2012). "Our results suggest that XRCC3 Thr241Met may act as a favorable prognostic indicator for lung squamous cell carcinoma patients." (PMID 23443124, 2012). "Our results suggest that the XRCC3 Thr241Met gene polymorphism plays an important role in the overall survival of Japanese lung squamous cell carcinoma patients without chemotherapy." (PMID 23443124, 2012).
lymph node metastases (2 papers, 2013 to 2015). "An association was confirmed between XRCC2 Arg188His and XRCC3 Thr241Met polymorphisms and TNBC progression, assessed by the degree of lymph node metastases and histological grades." (PMID 24728564, 2015). "And high expression of XRCC3 and RAD51 were associated with large tumor size and axillary lymph node metastasis respectively." (PMID 23977219, 2013).
mucositis (2 papers, 2015 to 2022). Mucositis is inflammation and damage of the mucous membranes lining the mouth and other parts of the gastrointestinal (GI) tract. "The XRCC3 Thr241Met was found to be significantly associated with radiation-induced acute skin toxicity and mucositis." (PMID 36494413, 2022). "In conclusion, the meta-analysis suggests that the XRCC3 p.Thr241Met polymorphism is significantly associated with a higher risk of radiation-induced early adverse effects such as acute skin toxicity and mucositis." (PMID 26091483, 2015).
basal cell carcinoma (1 paper, 2014). A carcinoma involving the basal cells. "Furthermore, significant association was also observed in XRCC3 C18067T polymorphism with both basal cell carcinoma risk (homozygote comparison TT versus CC: OR = 0.70, 95%CI = 0.53–0.92, P = 0.011; recessive model TT versus." (PMID 24454720, 2014). "Further subgroup analysis by subtype of nonmelanoma, we found that the XRCC3 C18067T polymorphism contributed decreased risk to not only basal cell carcinoma (homozygote comparison TT versus." (PMID 24454720, 2014).
basal cell carcinoma of skin (1 paper, 2012). "MC1R variants were associated with susceptibility to basal cell carcinoma of skin and there is an interaction with host factors and the XRCC3 gene." (PMID 22759494, 2012).
colorectal adenoma (1 paper, 2006). An adenoma that arises from the colon or rectum. "In the present study we used a case-control design to test the association between five amino acid substitution variants of DNA repair genes, XRCC1 (Arg194Trp), XRCC1 (Arg280His), XRCC1 (Arg399Gln), XRCC3 (Thr241Met) and XPD (Lys751Gln), and colorectal adenoma/cancer risk in a Norwegian cohort." (PMID 16542436, 2006).
desmoid fibromatosis (1 paper, 2022). "Whole chromosome 5 or 11 gain was common for F9 MB and M6 prolactinoma or sarcoma, respectively, and conversely, whole chromosome 14 loss, including the XRCC3 site, was common for the M6 MB and F9 desmoid fibromatosis that occurred post-radiotherapy." (PMID 35978432, 2022).
differentiated thyroid carcinoma (1 paper, 2017). Differentiated thyroid carcinoma (DTC), also known as papillary or follicular thyroid carcinoma, is a slow-growing malignancy usually presenting in adults as an asymptomatic thyroid mass. "As Yan and collaborators showed, the XRCC1 variant can interact with the XRCC3 variant to significantly increase differentiated thyroid carcinoma (DTC) susceptibility." (PMID 29178884, 2017).